TERT (telomerase reverse transcriptase)
Diseases named in the same sentence as TERT in open-access papers (continued):
Sharing a sentence is not in itself a finding about the gene and the disease.
cancer (continued). "Taken together, the TERT promoter mutation-mediated TERT expression may contribute to remote metastases of cancer cells via both telomere lengthening-dependent and independent mechanisms." (PMID 25474136, 2014). "For this study, polymorphisms in the TERT sequence were observed in Shih Tzus, Dachshunds, Irish Wolfhounds and Newfoundlands: four breeds that show large differences in size, expected lifespan, cancer susceptibility, and geographic origins." (PMID 24423165, 2014). "Clinical observations suggest that TERT promoter mutations may predict outcomes and also serve as markers of diagnosis or recurrence in a number of cancer types." (PMID 24742867, 2014). "For example, the HBx-MLL4 chimera fusions potentially produce cancer-specific proteins that can be specifically targeted therapeutically, and the TERT gene activation modes may suggest different diagnostic markers for a subset of HCC patients." (PMID 25159915, 2014). "Therefore, to further explore the association between the TERT rs2736098 polymorphism and cancer risk, a meta-analysis based on previously published studies and our case-control study was also performed." (PMID 24260099, 2013). "Consistent with this hypothesis, we found TERT mRNA expression levels to be associated with genotype at rs4975596/rs7736074 in multiple cancer types." (PMID 24152305, 2013). "In addition, the TERT rs2736098 variant A allele showed a marginally significant association with overall cancer risk." (PMID 24260099, 2013). "Subsequent studies found TERT promoter mutations in a wide array of other major human cancers." (PMID 24260374, 2013). "A single nucleotide polymorphism (SNP) rs2736100 located in intron 2 of TERT, has been hypothesised to be associated with the risk of cancer development by many researchers, however, the results are conflicting and heterogeneous." (PMID 22221621, 2012). "Mutations in the coding regions of TERT can affect telomerase activity and telomere length, and generate severe clinical phenotypes, including bone marrow failure syndromes and a substantive increase in cancer frequency." (PMID 23226346, 2012). "As CIN of cancer cells could also be caused by telomere erosion, we examined the expression of the TERT gene encoding telomerase reverse transcriptase." (PMID 21352579, 2011). "As a universal tumor-associated antigen, TERT is an ideal target for cancer therapy." (PMID 20856939, 2010). "Additionally, genome-wide association studies implicated TERT as a strong susceptibility locus (chr 5p15.33) for a large variety of cancers." (PMID 19936245, 2009). "Moreover, TERT-associated alterations manifest as elevated mRNA expression levels, and their potential as tumor biomarkers for early diagnosis and prognosis has been demonstrated across various cancers, including bladder cancer and glioma." (PMID 40723883, 2025). "Altered TERT isoform ratios might modulate cellular longevity and replicative potential at homeostasis and in response to environmental factors, thus selectively contributing to the reduced or elevated cancer risk conferred by this locus." (PMID 39802763, 2024). "In contrast, the five promoter mutations that could not be explained by elevated UV damage are known non-coding driver mutations (TERT promoter mutations) or occur upstream of a known cancer gene (BLCAP41,42) or a gene important for melanocyte differentiation (KBTBD843)." (PMID 37169747, 2023). "The early onset of TERT promoter mutations is highly consistent with recent observations that oncogenic genomic alterations may take place in childhood or adolescent periods long before cancer formation." (PMID 36713366, 2022). "However, although hTERT promoter (hTERTp) mutations are the primary cancer-associated genetic mechanism of TERT upregulation, additional genetic and epigenetic events may also contribute to hTERT upregulation in cancer cells." (PMID 35887633, 2022).
cancer (continued). "The coexistence of shortened telomeres with TERT transcription and telomerase activation in the late stage of carcinogenesis has long been observed, but it remains elusive whether they have a causal relationship in TCs and other cancer types." (PMID 36394204, 2022). "Thus, TERT expression is a hallmark of cancer cells that exhibit telomerase activity." (PMID 35741087, 2022). "Thus, it cannot be concluded whether certain cancer cells with driver mutations other than those of the TERT promoter mutations existed in the analyzed eHCC tissues." (PMID 35158835, 2022). "Indeed, mutations at the TERT promoter region are the most frequent, non‐coding mutation in cancer." (PMID 35920280, 2022). "Two hotspot mutations, C228T and C250T, in the TERT promoter region have been proposed as novel mechanisms for the activation of telomerase in malignant cells, and act as important biomarkers for predicting aggressive clinical behavior in various types of cancer." (PMID 35135543, 2022). "Interestingly, the TERT promoter harbors the most frequent recurrently mutated sites across non-coding regions found in multiple cancer types, and in ~90% of human cancers TERT expression is upregulated." (PMID 35851062, 2022). "Therefore, it is important to reexamine the therapeutic potential of chemical inhibition of telomerase activity in cancer cells with TERT promoter mutations, as well as some new emerging therapies, such as gene editing, targeted transcription factors, and telomerase inhibition and TERT vaccines." (PMID 35903534, 2022). "Therefore, the differential distribution of TERT promoter mutations across cancer types may reflect different aetiologies, APOBEC3- and aging-induced deamination on one hand, versus UV-induced mutations on the other." (PMID 34944589, 2021). "In addition, a comparative analysis of the MBCs subjected to WES or targeted cancer gene sequencing (n = 44) revealed that MBCs harboring TERT promoter hotspot mutations or gene amplification (n = 6) more frequently harbored PIK3CA than TERT wild-type MBCs (n = 38; p = 0.001; Fisher’s exact test)." (PMID 33863915, 2021). "This upregulation enables unlimited replication of cancer cells TERT activation in cancer occurs through a variety of mechanisms, including activating promoter mutations, alterations in promoter DNA methylation, chromatin remodeling, copy number alterations, and alternative splicing of TERT." (PMID 34127009, 2021). "A previous study found that the effect of TERT promoter mutation on the transcriptional regulation varies in each cell differentiation stage, suggesting that the difference in TERT promoter mutation frequency is responsible for the difference in cell‐of‐origin of cancer cells." (PMID 34477310, 2021). "Moreover, transcription is driven by recruitment of the transcription factor GA binding protein transcription factor subunit alpha (GABPA) and subunit beta (GABPB) to the mutated promotor, leading to an increased transcription of the mutated TERT allele in cancer cells." (PMID 34680452, 2021). "This intriguing observation could be the result of additional immunosuppression imposed by cancer onset and/or the diversion of residual immune responses towards cancer-associated antigens different from Survivin or TERT and warrants further investigation in larger series." (PMID 34746013, 2021). "Moreover, independently from its activity as functional telomerase inhibitor, BIBR1532 induces the down-regulation of TERT expression, which in turn further weakens TA and provides additional anti-cancer effects linked to impairment of its extra-telomeric functions." (PMID 33553285, 2020). "Recent studies have identified several single nucleotide polymorphisms (SNPs) in the TERT gene, including regulatory regions, which can affect TERT expression and constitutive telomere length and have been associated with risk and/or outcome for several human cancers." (PMID 33113831, 2020).
cancer (continued). "In the hypomethylated proximal promoter region, cancer cell lines with apparent biallelic expression (BAE) of TERT had significantly lower methylation compared to lines with monoallelic expression (MAE) of TERT, consistent with decreased methylation here to be associated with TERT expression." (PMID 33245585, 2020). "Thus, TERT expression in cancer lines may be canonical after all, in terms of its association with low DNA CpG methylation." (PMID 33245585, 2020). "The original quest to analyze the TERT promoter for mutations was driven both by the question of how telomerase is overexpressed in human cancer cells and by the question of whether mutations in noncoding regions play a direct role in driving cancer." (PMID 33024276, 2020). "We find that, generally, hypermethylation of TERT promoter sequences in cancer cells is associated with repressed chromatin/expression, and the remaining unmethylated alleles marked with open chromatin marks are largely responsible for the observed TERT expression in cancer cells." (PMID 32468444, 2020). "However, if expression and activation of TERT alleles is entirely advantageous to cancer cells, then it is unclear why cells with unmethylated alleles would not, over time, dominate the population, resulting in the majority of alleles being hypomethylated rather than what we observe here." (PMID 32468444, 2020). "While the TERT promoter contains a strikingly hypermethylated distal promoter region in human cancer cells, here we found that hypomethylation at the proximal promoter, flanking the transcription start site region, is also strongly associated with active TERT transcription in cancer cells." (PMID 33245585, 2020). "Moreover, transcriptional profiling of normal and TERT-immortalized fibroblasts identified 172 differentially expressed genes in TERT-immortalized cells, one of them epiregulin being a potent growth factor associated with cancer." (PMID 31911897, 2019). "A spectacular example was identified in several cancer entities involving the promoter of the TERT gene, in which two recurrent mutations have been shown to create new binding sites for Ets-family transcription factors, leading to a strong over-expression of the TERT oncogene." (PMID 31109337, 2019). "However, a number of problems (such as unstable TERT mRNA and enzymatic activity) impede reliable utility of a direct TERT expression or telomerase activity assay for cancer diagnostic or monitoring purpose, whereas widespread TERT promoter mutations in different tumors pave new avenues." (PMID 31285550, 2019). "Moreover, TERT copy number gain co‐occurred with TERT hotspot mutations in some HCC and PDTC, suggesting that it may cooperate with hotspot mutations in TERT reactivation and cancer progression." (PMID 31408918, 2019). "In addition, the TERT promoter hypermethylation has been implicated in cancer prognostication." (PMID 31284662, 2019). "Overall, we can speculate that short telomeres are predisposed to genomic instability, and hence the occurrence of cancer-driving mutations, which include TERT promoter mutations; subsequently, telomerase activation maintains telomere length and sustains cancer evolution and progression." (PMID 31200515, 2019). "In addition, the weak nature of this interaction could be required to only mildly activate TERT because only 1000 molecules of TERT are present in a cell and that hyperactivation of TERT by stronger activators could cause adverse effects in cancer cells." (PMID 30093619, 2018).
cancer (continued). "Similar to retrovirus, HBV genes could insert into host cancer genes such as those encoding telomerase reverse transcriptase (TERT), mixed-lineage leukaemia protein 4 (MLL4) and cyclin E1 (CCNE1) causing oncogenesis, and could exert effects on cell functions persistently." (PMID 28640739, 2017). "In the setting of the MED12-mutant pathway, borderline and malignant PTs might stem from a pre-existing FA and progress to a malignant phenotype following the acquisition of additional genetic alterations in cancer genes, including TERT promoter mutations and TERT amplification." (PMID 29043292, 2017). "In addition to germline TERT variants contributing to cancer risk more recently, the hotspot TERT promoter mutations named C228T and C250T were identified as a key genetic event to activate telomerase in different types of cancer." (PMID 26934125, 2016). "Furthermore, to date only one intergenic driver of cancer—an activating C > T mutation in the TERT promoter at chr5:1,295,228—has been confirmed, and although this is included in the excess sites with 7 SNVs, the remaining 1,186 excess sites are unlikely to be under such selection." (PMID 27688957, 2016). "The cancer-specific telomerase activation is primarily determined by telomerase reverse transcriptase (TERT) activity, which may be re-activated by epigenetic regulation, TERT amplification or TERT promoter mutations." (PMID 27056898, 2016). "In addition, although numerous studies have been conducted, the subcellular localization of the TERT protein and the association of such with cancer metastasis remains unclear." (PMID 25435972, 2015). "Thus far, although non-coding mutations are more numerous than coding mutations, very few recurrent cis-regulatory mutations have been found, and recent pan-cancer analyses concluded that in fact only one potential cis-regulatory mutation, in the TERT promoter is highly recurrent." (PMID 26562774, 2015). "Therefore, genetic variants and somatic alterations in the TERT gene may affect telomerase function and contribute to the development of cancer as well as the outcome of chemotherapy." (PMID 26298771, 2015). "Interestingly, all TERT promoter mutations associated with cancer formation thus far generate novel binding sites for the ETS (E26 transformation-specific) family of transcription factors and are located close to the translational start site of TERT (e.g., −57A/C, −124C/T, and −146C/T)." (PMID 26194807, 2015). "The next crucial step was to elucidate how TERT promoter mutations might contribute to cancer." (PMID 26194808, 2015). "Given that the diagnostic accuracy of methylated TERT might vary in the histological subtype of each cancer type, we intended to stratify each cancer type depending on the histological or molecular subtypes and evaluate the performance difference of methylated hTERT." (PMID 26734575, 2015). "The somatic mutations of the TERT promoter have recently been identified in different types of human malignancies, and studies have also shown that these mutations may serve as a new cancer diagnostic and prognostic marker." (PMID 24742867, 2014). "However, the underlying mechanism of TERT reactivation in cancer cells was an unresolved issue." (PMID 24726063, 2014). "In summary, CR is able to reduce the increased cancer incidence associated to TERT over-expression, which together with the increased “health span” associated to TERT over-expression could explain the synergistic effects of TERT and CR in increasing longevity (see summary table)." (PMID 23349740, 2013). "This meta-analysis suggests that the TERT rs2736100 polymorphism may be a risk factor for cancer." (PMID 22221621, 2012). "Thus, the evidence that the TERT locus contains risk factors for cancer is compelling." (PMID 21929825, 2011).
cancer (continued). "Simultaneously, the mild thermal conditions activate transcription from the Hsp70 promoter, inducing in situ small interfering RNA synthesis for TERT gene knockdown to synergize with MTT-mediated cancer treatment." (PMID 41614641, 2026). "In B-acute lymphoblastic leukemia, a cancer that originates from a B-cell precursor lineage and is particularly common among pediatric patients, high TERT levels and telomerase activity correlate with poor clinical outcomes and lower survival rates." (PMID 40227701, 2025). "The transcription of telomerase reverse transcriptase (TERT) is repressed in most adult human cells but is active in many cancers, allowing cancer cells to replicate excessively." (PMID 40799400, 2025). "In contrast, telomerase reactivation—primarily through increased expression of TERT—is observed in the vast majority of human cancers, representing a common mechanism for cellular immortalization." (PMID 40725486, 2025). "The subsequent binding reactions enhance the transcription of TERT, ultimately leading to telomere maintenance and the sustained proliferation of cancer cells." (PMID 39934880, 2025). "Our data provides compelling evidence that peptide-gold nanoparticles, particularly AuNP-p-CPS62, possess potent anti-cancer ability by down-regulating the expression of c-Myc, TERT, and BRAF via blockade of c-Myc/TERT interaction." (PMID 40860184, 2025). "This suggests that when considering TERT subcellular localization as a biomarker, the specific subtype of cancer must be taken into account." (PMID 39871386, 2025). "Vaccines that elicit an immune response against TERT-expressing cells have shown promise in preclinical studies, offering a potential route to specifically target cancer cells while sparing normal cells." (PMID 40467649, 2025). "The dysregulation of TERT can contribute to genomic instability and promote tumorigenesis by allowing cancer cells to bypass normal cellular senescence mechanisms." (PMID 40070565, 2025). "The overwhelming understanding, particularly in cancer cells, suggests that the reactivation of TERT drives telomere elongation/maintenance." (PMID 41026782, 2025). "Reactivation of the telomerase catalytic subunit (TERT) is a critical mechanism by which cancer cells bypass senescence and attain unlimited proliferative capacity, a hallmark of many malignancies." (PMID 40508012, 2025). "Induced pluripotent stem cells and cancer cells express higher levels of TERT Delta 2–4 compared to primary human bronchial epithelial cells." (PMID 40000722, 2025). "Since mitochondrion is considered a mediator of tumorigenesis, clarifying the mitochondrial TERT mechanism of action and its connection with mitochondrial functions will help better define the role of mitochondria in cancer." (PMID 41144538, 2025). "This inhibition of TERT activity leads to progressive telomere shortening that induces senescence and apoptosis in cancer cells." (PMID 40467649, 2025). "Whereas some cancers utilize the alternative lengthening of telomeres (ALT) pathway to maintain telomeres, many cancers are known to acquire somatic mutations in the TERT promoter that result in increased TERT expression and telomerase activity." (PMID 41279560, 2025). "The TERT gene promotes cancer cell immortalization by serving as the catalytic component of the telomerase complex." (PMID 41293148, 2025). "By regulating TERT splicing, these variants may contribute to fine-tuning cellular longevity and replicative potential in the context of stress due to tissue-specific endogenous and exogenous exposures, thereby influencing the cancer risk conferred by this locus." (PMID 39956830, 2025).